IGF1 (insulin like growth factor 1)
Diseases named in the same sentence as IGF1 in open-access papers (continued):
Sharing a sentence is not in itself a finding about the gene and the disease.
malnutrition (continued). "The usefulness of serum insulin-like growth factor-1 concentration as a specific marker for detecting malnutrition is clinically controversial." (PMID 38260080, 2023). "IGF-1 is a central hormone in growth regulation and is closely related to nutritional status, and malnutrition significantly reduces serum IGF-1 levels and can return to normal concentrations after re-feeding." (PMID 36979134, 2023). "SIRT1-dependent negative regulation of GH-induced IGF-1 production seems to be an adaptive mechanism under fasting conditions and malnutrition." (PMID 37895086, 2023). "Like systemic inflammation or chronic liver disease, fasting and malnutrition decrease the expression of hepatic GH receptors, with consequent reduction of IGF-1 levels, through resistance to GH." (PMID 36973824, 2023). "In terms of growing, fasting induces GH resistance in the liver, leading to a decrease in the serum IGF-1 levels as one of the adaptive mechanisms for malnutrition." (PMID 37895086, 2023). "In the course of malnutrition, high expression of miR-486 leads to a decrease in muscle mass through activation of the insulin-like growth factor-1/ankyrin (IGF-1/Akt) signaling pathway." (PMID 35160257, 2022). "Thus, the deregulation of certain key components of the mTOR pathway in childhood malnutrition may be attributed to a combinatory effect of increased levels of pro-inflammatory cytokines leading to reduced levels of IGF-1 and growth hormone and a deficiency of essential amino acids in circulation." (PMID 35458174, 2022). "Postnatal thymus atrophy is a well-known effect of malnutrition in both man6,7 and rat10, and low IGF-1 level is considered a reliable marker in malnutrition." (PMID 35260716, 2022). "IGF-1 secretion is influenced also by malnutrition, thyroid hormone, sex hormones, chronic diseases and inflammation and anorexia nervosa." (PMID 35250894, 2022). "Thymus growth and function is regulated by several hormones including Leptin, Prolactin and Growth hormone, mediated by insulin-like growth factor 1, all of which are low in malnutrition." (PMID 33397296, 2021). "The rise in GH following exercise in our study was not triggered by an increase in ghrelin, baseline hypoglycemia, or by low levels of IGF-1, all of which can stimulate GH secretion in fasting or malnutrition." (PMID 34485418, 2021). "An adverse effect of malnutrition on the growth process with blockage of IGF-1 secretion by sirtuin 1 (SIRT1) was described." (PMID 34445772, 2021). "Decreased serum IGF-1 levels due to malnutrition during high-dose polychemotherapy and dexamethasone can also affect linear growth." (PMID 33815276, 2021). "Under insufficient nutrition or malnutrition, the impaired IGF-1-mediated macromolecular synthesis creates an obstacle to muscle mass maintenance." (PMID 35010979, 2021). "In animals with anorexia nervosa, hunger, and malnutrition, GH content increases, while IGF-1 content decreases." (PMID 33435531, 2021). "The production of IGF1 is inhibited by malnutrition, insusceptibility to the growth hormone, and growth hormone receptor deficiency." (PMID 34205470, 2021). "Factors that negatively affect linear growth are increased levels of inflammatory cytokines such as interleukin-6 (IL-6) and tumor necrosis factor-α (TNF-α), malnutrition, suppression of serum IGF-1 levels, and disease severity." (PMID 33446154, 2021). "In a fasting state or malnutrition, it intensifies the adaptive processes, i.e., gluconeogenesis and fatty acid oxidation, reducing the production of IGF-1, the factor which has a hypoglycaemic effect." (PMID 34445772, 2021). "Inflammation and malnutrition can also result in GH resistance as suggested in high sensitivity C-reactive protein (hsCRP) and GH, IGF-1 and IGFBP-3 levels in malnourished and often infected infants and children in Fortaleza, Brazil." (PMID 33117295, 2020).
malnutrition (continued). "The linear growth is mediated by the growth hormone (GH) and by the IGF1 growth factor, which become abnormal during periods of malnutrition." (PMID 32455002, 2020). "The classic endocrine system response to the stress of malnutrition includes high basal GH and cortisol levels with a low circulating concentration of IGF-1." (PMID 33117295, 2020). "We also studied the effects of insulin-like growth factor 1 (IGF1), a hormone and paracrine mediator critical for growth and organ function, which is invariably reduced in all forms of malnutrition and wasting, including anorexia nervosa." (PMID 27716401, 2016). "Patients suffering from malnutrition with GH hypersecretion and low IGF-1 levels are considered GH-resistant." (PMID 25909895, 2015). "Changes in the GH/IGF-1 axis are well-documented in cirrhosis, and the peptides involved have been proposed as markers of hepatocellular dysfunction, malnutrition and survival in this category of patients." (PMID 26186540, 2015). "In conclusion, oral administration of leucine improved GH resistance in rats with malnutrition by promoting IGF-1, reducing IGF-1 degradation, and facilitating GHR synthesis in the liver." (PMID 25909895, 2015). "The reduced delivery of solutes to the IVD due to the constriction of the vascular network surrounding the tissue determined the level of malnutrition and impaired supply of anabolic agents (i.e., IGF-1) to disc cells." (PMID 26301590, 2015). "Protein and energy content of the diet influences plasma IGF-1 concentrations, and IGF-1 levels are reduced during conditions of energy restriction such as short-term fasting and malnutrition." (PMID 25909895, 2015). "This is a desirable outcome, since IGF-1 plays an important role in GH resistance during malnutrition." (PMID 25909895, 2015). "Our study revealed that leucine supplementation resulted in the rapid recovery of the IGF-1 system in rats with severe malnutrition." (PMID 25909895, 2015). "The corresponding malnutrition status evidenced in cirrhosis has been suggested by some authors to be related to the limited production of IGF-1 by the diseased liver." (PMID 24804205, 2014). "While GH measurement has become more sensitive in the recent decades, IGF-1 measurements can be misleading in situations such as malnutrition, liver disease and kidney failure." (PMID 25511633, 2014). "More recently, abnormality in the growth hormone/IGF-1 axis has been an important factor in the development of malnutrition in CRF patients." (PMID 28197445, 2013). "In subjects undergoing protein-caloric restriction, it has been observed a significant reduction in circulating IGF-1 levels that has been correlated to the typical alteration in urea nitrogen urinary excretion occurring in malnutrition." (PMID 24152751, 2013). "The tight relationship between low levels of IGF-1 and malnutrition has been also described during celiac disease, where a rapid normalization of serum IGF-1 followed a gluten-free diet." (PMID 24152751, 2013). "Even similar reports were found favouring malnutrition before initiation of dialysis, indicating reductions in serum transferrin, serum cholesterol, serum IGF-1, percentage of body weight and urinary creatinine excretion as renal function deteriorated." (PMID 28197445, 2013). "Insulin-like growth factor-1 (IGF-1) is low in AN patients due to malnutrition." (PMID 40130112, 2025). "A conceptual model suggests that malnutrition inhibits hepatic IGF-1 synthesis, this hypothesis was supported by mouse models in which IGF-1 levels are reduced during malnutrition." (PMID 41292641, 2025). "Female patients may be particularly vulnerable due to lower baseline muscle mass, smaller body size, and sex-specific hormonal differences (e.g., lower testosterone and IGF-1 levels), which amplify the physiological consequences of malnutrition." (PMID 41141484, 2025).
malnutrition (continued). "Additionally, malnutrition is often accompanied by endocrine dysregulation, characterized by decreased levels of anabolic hormones (e.g., IGF-1, testosterone) and predominance of catabolic signals (e.g., cortisol, inflammatory cytokines)." (PMID 41141484, 2025). "Low serum IGF-1 has also been shown as a biochemical marker for malnutrition." (PMID 40589518, 2025). "Insulin-like growth factor-1 (IGF-1) levels, which share downstream signaling cascades with insulin and promote muscle growth, are frequently reduced in conditions such as chronic diseases, inflammation, and malnutrition." (PMID 41464556, 2025). "As an indication of malnutrition and resultant wasting syndrome, elevated asparagine synthetase (Asns) and reduced insulin growth factor 1 (Igf1) expression in livers from LEC Srebf2–/– mice were found, which resemble Plagl2-knockout mice in which lacteals in jejunum are also dilated." (PMID 41122969, 2025). "Additionally, other non-steroidal causes of bone mineral density loss in these patients include reduced physical activity and malnutrition, leading to poor production of insulin-like growth factor-1, crucial for stimulating osteoblastic activity." (PMID 39796035, 2024). "Therefore, in cases of malnutrition conditions, an increased secretion of GH from the pituitary and decreased secretion of IGF-1 from the liver at the same time (as, for example, in anorexia nervosa) is beneficial for the body (to maintain glucose levels)." (PMID 39062007, 2024). "Therefore, GH and IGF-1 levels should be carefully evaluated taking into account the nutritional state, as low insulin levels present in malnutrition make the liver resistant to GH contributing to reduce even more circulating IGF-1 levels." (PMID 37191429, 2023). "In addition, the relative resistance to GH and the decreased expression of GH receptors during malnutrition are also the reasons for the decreased IGF-1 level." (PMID 37111069, 2023). "The fT4 levels in CKD patients have been correlated with higher levels of markers of inflammation, malnutrition (lower prealbumin, IGF-1), increased endothelial dysfunction, poor cardiac function, poor survival as well as cardiovascular mortality in some studies." (PMID 37623811, 2023). "This sensitivity might be the reason of the significant differences in expression between the diets observed in this study, especially since malnutrition is known to reduce circulating IGF1 in mice." (PMID 35749523, 2022). "Higher alcohol intake may decrease IGF-1 through its inhibitory effect on growth hormone secretion, liver dysfunction, and/or malnutrition." (PMID 34607837, 2021). "In addition, at the end of the experiment, we measured markers of malnutrition and stress, including IGF-1, leptin, corticosterone, and IgA levels." (PMID 34207946, 2021). "Indeed, antiestrogens such as tamoxifen have been associated with reductions in serum insulin-like growth factor-1 (IGF-1), and low IGF-1 is associated with malnutrition." (PMID 35011059, 2021). "However, its concentration changes are not sufficiently specific to be useful clinically as a marker of malnutrition, and serum IGF-1 has less been used in clinical trials." (PMID 31159248, 2019). "Serum IGF-1 is less influenced by inflammation and falls during malnutrition." (PMID 31159248, 2019). "The poor synthesis of IGF-1 could depend on a primitive defect of the axis, but also from malnutrition and hypermetabolic status of these patients." (PMID 30744584, 2019). "However, during states of pure malnutrition (such as in anorexia nervosa), IGF-1 levels are low, demonstrating GH resistance." (PMID 27712965, 2017). "As this model differs from ours by its continuous postpartal malnutrition until day 21, such regimen might exert its influence on mammary gland development rather via changes in the actions of insulin and IGF-1, than via alteration of ovarian steroid levels." (PMID 24955840, 2014).
malnutrition (continued). "Risk factors for CKD–mineral and bone disorder (CKD–MBD) include nutritional vitamin D deficiency, secondary hyperparathyroidism, increased fibroblast growth factor 23 (FGF-23), altered growth hormone and insulin-like growth factor-1 axis, delayed puberty, malnutrition, and metabolic acidosis." (PMID 24605319, 2014). "In addition, several conditions can lower IGF-1 levels, including malnutrition, poorly controlled diabetes, and hepatic or renal failure, as well as estrogen therapy and hypothyroidism." (PMID 24272033, 2014). "With weight SDS scores significantly below the height SDS scores, one should consider the possibility that malnutrition in the baseline state may have contributed to selective depressions of IGF-1." (PMID 25177352, 2014). "This case demonstrates that NTI and low IGF-1 levels may occur in infants with malnutrition." (PMID 41777940, 2026). "Several factors contribute to this decline, including malnutrition, immobility, neurological changes, and chronic illness along with hormonal changes related to aging, such as alterations in insulin-like growth factor-1 (IGF-1), growth hormones, sex hormones, and glucocorticoids." (PMID 40303597, 2025). "It seems that SIRT1, which regulates the JAK2/STAT pathway, may be involved in peripheral GH resistance and be responsible for the reduced IGF-1 concentration in some conditions (e.g., malnutrition) that require increased glucose production to prevent hypoglycaemia." (PMID 37895086, 2023). "Moreover, it has been recently proposed that reduced hepatic production of insulin-like growth factor-1 (IGF-1) in ascitic liver disease could be one of the factors contributing to malnutrition in cirrhotic patients." (PMID 28472963, 2017). "Our study aimed at investigating if long-term leucine supplementation could modulate GH-insulin-like growth factor (IGF)-1 system function and mammalian target of rapamycin (mTOR)-related signal transduction in skeletal muscles in a rat model of severe malnutrition." (PMID 25909895, 2015). "Given that IGF1 and IGF2 levels are gold standards for identifying malnutrition, and that they are major upstream regulators of the PI3K-AKT signaling pathway." (PMID 37872623, 2023). "Plasma levels of insulin-like growth factor 1 (IGF-1) also indicated the existence and severity of malnutrition." (PMID 37742012, 2023). "Our findings of a clear-cut upregulation of muscle IGF-1 by amino acids may thus contribute to new understanding of factors in control of muscle protein metabolism; such as factors to maintain muscle function in progressive disease with malnutrition and flux of amino acids." (PMID 35802556, 2022). "The reduction of body weight gain, thymus and pancreas weights, small intestinal mucosal thickness and IGF-1 plasma levels in rats exposed to MRP-rich diets, as found in the present study, speak in favor of malnutrition and immune dysfunction." (PMID 35260716, 2022). "Furthermore, CD children with growth failure have normal growth hormone (GH) secretion but diminished plasma concentration of insulin-like growth factor-1 (IGF-1), suggesting a certain degree of GH resistance that may be related to malnutrition and inflammation." (PMID 27529220, 2016). "Our study clearly demonstrated that serum IGF-1 and IGFBP-3 levels were dramatically lower in rats with malnutrition." (PMID 25909895, 2015). "Reduced hepatic IGF-1 and IGFBP-3 mRNA expression and serum protein levels observed in the rats with malnutrition in our study confirm the findings of previous studies." (PMID 25909895, 2015). "Traditional risk factors for CKD–BMD include vitamin D deficiency, secondary hyperparathyroidism, disturbance of the growth hormone (GH)/insulin-like growth factor-1 (IGF-1) axis, delayed puberty, malnutrition, and metabolic acidosis." (PMID 24605319, 2014).
malnutrition (continued). "Chronic micro-inflammatory are recognized as one of the primary contributors to malnutrition in CKD patients, resulting in PEW by promoting muscle catabolism, triggering anorexia, reducing insulin-like growth factor-1 (IGF-1) secretion, and decreasing activity levels." (PMID 39950124, 2025). "IGF-1 levels can be influenced by various factors, including age, pubertal stage, chronic illness, and malnutrition, while IGFBP-3 offers no significant advantage over IGF-1 in older children." (PMID 40598150, 2025). "In this study, sarcopenic patients had significantly lower %IGF-1 levels than non-sarcopenic patients, and lower %IGF-1 levels were significantly associated with each item related to malnutrition, portal hypertension, and hepatic reserve function in CLD." (PMID 38024081, 2023). "IGF-1 is mainly synthesized in the liver, and the liver reduces IGF-1 production during the early lactation period for negative energy balance, malnutrition, disease, or inflammation, which in turn affects the concentration of IGF-1 in the blood." (PMID 38067044, 2023). "Thus, it appears that in children with malnutrition, the level of SIRT1 is increased to inhibit peripheral IGF-1 production and maintain homeostasis." (PMID 37895086, 2023). "A new parameter, that has not been extensively studied in this setting as malnutrition biomarkers yet, is IGF-1." (PMID 33488571, 2020). "Serum IGF-1, transferrin and iron levels, and all transferrin isoform patterns were not significantly different in mildly malnutrition group from other two groups." (PMID 25562020, 2014). "In addition, a reduction in food intake and nutritional status can reduce IGF-1 activity, which is common in CKD patients with malnutrition/ACS." (PMID 22537670, 2012). "It has been described that malnutrition could change the GH-IGF-1 pathway by producing GH resistance, inhibiting hepatic expression of GHR, and IGF-1 mRNA, as well as precipitating the disintegration, and reducing the bioactivity of IGF-1." (PMID 36374927, 2022). "However, reduced protein translation is thought to facilitate Dietary Restriction (DR, defined as reduction in food intake without malnutrition) mediated lifespan extension, but not Insulin/IGF-1-dependent longevity." (PMID 23820781, 2013). "Compared to their without malnutrition exposure risk counterparts, the with malnutrition exposure risk group exhibited significantly elevated levels of SHBG and HbA1c and reduced C-peptide, triglycerides, uric acid, hemoglobin, IGF-1, AST, ALT, weight, BMI, albumin, prealbumin, and transferrin." (PMID 39020340, 2024).